SMIM19 (small integral membrane protein 19)
Synonyms: C8orf40
Tractability: Antibody: UniProt predicts a signal peptide or a membrane-spanning region. PROTAC: ubiquitination databases record sites on it.
Gene: Protein-coding gene on chromosome 8 (42,541,155 to 42,555,195, forward strand). Ensembl gene ENSG00000176209.
Subcellular location: Membrane
Subcellular location (Human Protein Atlas): Nuclear speckles
Gene Ontology:
Molecular function: protein binding
Cellular component: membrane
Genetic constraint (gnomAD): Loss-of-function variants: 6 observed, 13.91 expected, observed/expected ratio (o/e) 0.43, 90% interval 0.23 to 0.85. The upper end of that interval is the gene's LOEUF score, 0.85, which puts it in group 3 of 6, group 1 being the genes least tolerant of losing a copy. Missense variants: 138 observed, 137.13 expected, observed/expected ratio (o/e) 1.01, 90% interval 0.88 to 1.16. Synonymous variants: 46 observed, 45.22 expected, observed/expected ratio (o/e) 1.02, 90% interval 0.8 to 1.3.
Homologues: Orthologues: chimpanzee SMIM19 (100% identical), macaque SMIM19 (100% identical), pig SMIM19 (93% identical), guinea pig SMIM19 (93% identical), dog SMIM19 (92% identical), mouse Smim19 (86% identical), rat Smim19 (83% identical), tropical clawed frog smim19 (72% identical), zebrafish smim19 (70% identical).